RNU1-4 (RNA, U1 small nuclear 4)
Synonyms: HSD6; U1E2; HSD2; U1D2; HSD5; U1B2; U1F; HSD7; RNU1; RNU1D2; RNU1E2; RNU1F1; RNU1G1; RNU1G2
Gene: Small nuclear RNA gene on chromosome 1 (16,740,516 to 16,740,679, forward strand). Ensembl gene ENSG00000207389.
Gene Ontology:
Molecular function: pre-mRNA 5'-splice site binding
Biological process: mRNA 5'-splice site recognition
Cellular component: U1 snRNP
Homologues: Paralogues in human: RNU1-1 (100% identical), RNU1-2 (100% identical), RNU1-27P (100% identical), RNU1-28P (100% identical), RNU1-3 (100% identical), RNVU1-18 (100% identical), RNVU1-29 (100% identical), U1 (100% identical), RNVU1-28 (99% identical), RNVU1-7 (99% identical), RNVU1-31 (99% identical), RNU1-89P (97% identical), and 134 more.